PLXNB3 (plexin B3)
Diseases named in the same sentence as PLXNB3 in open-access papers (continued):
Sharing a sentence is not in itself a finding about the gene and the disease.
tumor (continued). "The results of CCK-8 and EdU assays have indicated that the administration of rSEMA5A could significantly enhance the proliferation ability of PLXNB3-overexpressed tumor cell AsPC1PLXNB3-OE, while this effect would be lost once TSP domain was cut off." (PMID 36741230, 2023). "When only 1000 cells were injected (such that BCSCs were limiting), tumors formed in 10/10 mice injected with NTC cells, but only 3/10 and 2/9 mice injected with either of 2 NARF-knockdown subclones, indicating that NARF plays a critical role in BCSC specification and tumor initiation for PLXNB3." (PMID 37768037, 2023). "Besides, we observed PanIN I and PanIN II positive for Plexin-B3 expression in the tumor cores present in the tissue microarray." (PMID 33669221, 2021). "Cancer cells, tumor stroma, and a normal human pancreas show a wide range of Plexin-B3 expressions." (PMID 33669221, 2021). "In summary, based on our systematic analyses of NRPs and PLXNs in terms of their expression, association with patient survival, immune subtype, and tumor infiltration, we found that NRP1, NRP2, PLXNA1, PLXNA3, PLXNB3, PLXNC1, PLXND1 were mainly associated with poor prognosis." (PMID 32640719, 2020). "There is a possible tendency for plexin-B3 to function as a putative tumor suppressor in HCC." (PMID 25780417, 2015). "Plexin-B3 immunoreactivity in the HCC samples was significantly lower compared with the corresponding adjacent non-cancerous tissue, and the loss of plexin-B3 expression was found to correlate with the patient gender and tumor size." (PMID 25780417, 2015). "Therefore, it is possible that the Sema5A/plexin-B3 signaling pathway may exert tumor promoting and suppressive effects depending on the type of malignancy." (PMID 25780417, 2015). "We also found that PLXNB3, one of the canonical receptors of SEMA5A, was also aberrantly overexpressed on M2 TAM-infiltrated metastatic niche resident tumor cell membranes." (PMID 36741230, 2023). "The results indicated that plexin-B3 expression is downregulated in HCC, and the expression levels correlate with gender and tumor size." (PMID 25780417, 2015). "IF tests have demonstrated that only PLXNB3 existed on M2 TAM-infiltrated niches and this receptor could be observed colocation in tumor cells and adjacent ECM." (PMID 36741230, 2023). "Primary tumor growth was not significantly affected by the expression of either of the 2 different shRNAs targeting PLXNB3." (PMID 37768037, 2023). "Interestingly, the knockdown of PLXNB3 also reduced the infiltration of CD163-positive M2 TAMs into metastatic niches, illustrating that the promotion effects of tumor cells and TAMs were reciprocal." (PMID 36741230, 2023). "Furthermore, the M2 TAM CM would lose its growth stimulation effects on PANC1 tumor cell once SEMA5A was eliminated via immune precipitation (IP), which have manifested the important roles of SEMA5A in PLXNB3-induced proliferation advantage." (PMID 36741230, 2023). "Low expression of FABP4 in tumor tissues (p < 0.05) was validated in five datasets, the lower expression of PLXNB3, INHBB and NKAIN4 in tumor tissues was verified in three datasets (p < 0.05), and the decreased expression of HOXC9 and was validated in one dataset, respectively (p < 0.05)." (PMID 35721480, 2022). "Knockdown of Plexin B3 in 231 cells did not induce any significant changes in morphology or cell migration speed when tumor cells were cultured alone." (PMID 36333352, 2022). "The IHC results revealed that the protein expression level of plexin-B3 was lower in the HCC samples compared with the corresponding adjacent non-cancerous tissue, and plexin-B3 underexpression was correlated with the patient gender and tumor size." (PMID 25780417, 2015). "Furthermore, 30 clinical CRC tissues (including tumor tissues and the corresponding adjacent tumor tissues as well as normal tissues) were collected, and the expression of FABP4, HOXC9, INHBB, NKAIN4, and PLXNB3 was determined using RT-PCR." (PMID 35721480, 2022).
tumor (continued). "Plexin-B3 expression was negative or low in the majority of HCC samples, with positive staining observed in the membrane and cytoplasm of the tumor cells in positive cases." (PMID 25780417, 2015).
cancer (8 papers, 2020 to 2025). A tumor composed of atypical neoplastic, often pleomorphic cells that invade other tissues. "Recent analysis of pan-cancer data from The Cancer Genome Atlas (TCGA) revealed that intratumoral expression of PLXNB3 is associated with reduced patient survival." (PMID 41562084, 2025). "Furthermore, our data suggest that the loss of Plexin-B3 directly or indirectly interferes with cell division or proliferation and induces cancer stem cell-like PC cells." (PMID 33669221, 2021). "In the future, SEMA5A-Plexin-B3-specific signal transduction and cell signaling, particularly in relation to the cancer stemness feature and whether the loss of Plexin-B3 is mechanistically required for the extra-pancreatic spread, needs evaluation." (PMID 33669221, 2021). "Our results suggest that the context-dependent pathological expression of Plexin-B3 in PC and the loss of Plexin-B3 results in increased in vitro and in vivo migratory potential that can directly or indirectly result in the induction of cancer stem cell-like characteristics." (PMID 33669221, 2021). "Our interest in investigating the role of Plexin-B3 in stem cell properties of PC cells came from various studies that demonstrate Plexin-B’s role in regulating the stemness of different cancers." (PMID 33669221, 2021). "The PLXNB subgroup were associated with both survival advantage and disadvantage of a number of cancer types, but PLXNB1 and PLXNB2 were more associated with better survival, while PLXNB3 was more associated with worse survival." (PMID 32640719, 2020). "Furthermore, Plexin-B3, acting together with the interaction with the Met proto-oncogene product’s receptor tyrosine kinase, promotes cancer stem cell motility and metastasis." (PMID 38133141, 2023). "Both NRPs, PLXNA1-A3, PLXNB1-B2, and PLXND1 had relatively higher expression and smaller heterogeneity, while genes PLXNA4, PLXNB3 and PLXNC1 had lower expression across all cancer types but with higher heterogeneity." (PMID 32640719, 2020). "PLXNB3 binds to and activates the MET receptor tyrosine kinase, leading to activation of the SRC non-receptor tyrosine kinase and subsequently focal adhesion kinase, which promotes cancer cell migration and invasion." (PMID 37768037, 2023).
neurodevelopmental disorder (2 papers, 2022 to 2024). A behavioral and cognitive disorder with onset during the developmental period that involves impaired or aberrant development of intellectual, motor, or social functions. "Plexin B3 has been characterized to be related to neurodevelopmental disorders." (PMID 38628398, 2024).
PLXNB3 also shares sentences with these, for which no sentence is quoted: metastatic tumor (2 papers); Alzheimer disease (1); Brain injuries (1); COVID-19 (1); Diabetes (1); iron deficiency (1); Jaundice (1); liver cirrhosis (1); lung squamous cell carcinoma (1); neurodevelopmental disabilities (1); pancreatic ductal adenocarcinoma (1); renal carcinoma (1).